UCP2 (uncoupling protein 2)
Diseases named in the same sentence as UCP2 in open-access papers (continued):
Sharing a sentence is not in itself a finding about the gene and the disease.
tumor (continued). "The present data indicate that UCP2, and potentially also COPS2, may function as tumour suppressors in CRC." (PMID 26148070, 2015). "Finally, ectopic expression of UCP2 in MCF7 breast cancer cells has been demonstrated to enhance proliferation, migration and matrigel invasion in vitro and to promote tumor growth in vivo." (PMID 23966948, 2013). "UCP-2 mRNA was elevated by over two-fold (P<0.01) in tumour-bearing mice, but no changes were found in pair-fed animals, relative to controls." (PMID 17047651, 2006). "Alternatively, the expression of PRPF40A and UCP2 may require additional stimulators, which are present in tumour microenvironment in vivo, but absent in vitro (e.g., more acute O2 deficit, cytokine release, and interactions with extracellular stroma)." (PMID 28258342, 2017). "Thus, a total of four tumours were found in ten two-year-old UCP2-ablated mice, but not a single wild-type littermate had developed a tumour by that age." (PMID 24281083, 2010). "However, UCP2 inhibition alone does not suppress tumor growth." (PMID 41486584, 2026). "However, although the TCA cycle function is enhanced by UCP2 content, the authors do not show whether this correlates with reduced tumor cell proliferation, migration or invasion." (PMID 36499405, 2022). "Given that PFKFB2 was activated in wild-type mice but not in UCP2 knockout mice during the skin carcinogenesis study, we speculated that UCP2 overexpression may bring a metabolic shift towards glycolysis by activating PFKFB2 as a potential novel mechanism of tumor promotion." (PMID 29221144, 2017). "Importantly, the combined therapy of trastuzumab and UCP-2 inhibitor Genipin significantly suppressed tumor cell growth and promoted apoptosis in vitro, indicating that UCP-2 inhibition might be a novel therapeutic target to enhance anti-tumor efficacy of trastuzumab." (PMID 34146128, 2021). "HIF1A-mediated LEP upregulation in an LKB1-depleted environment may augment the LUAD energetic burden via activation of downstream mitochondrial uncoupling players such as UCP2; however that regulation alone does not appear sufficient to confer lethality to LKB1 tumours." (PMID 39048991, 2024).
infection (15 papers, 2008 to 2025). The state of being infected such as from the introduction of a foreign agent such as serum, vaccine, antigenic substance or organism. "Overall, these data suggest Ld infection–associated increase in Ucp2 that causes mitochondrial detethering with ER and prevents the pro-inflammatory miR-122 entry via EVs into the infected macrophage to stop expression of pro-inflammatory cytokines." (PMID 35210329, 2022). "To investigate the effects of host UCP2 deficiency on L. infantum systemic infection, we evaluated parasite loads in the spleen and liver by limiting dilution after 8 weeks of infection." (PMID 23437414, 2013). "Nevertheless, we demonstrate here an enhanced resistance (Killing activity at 24 h) of UCP2-deficient macrophages to infection with the intracellular protozoan L. pifanoi." (PMID 23437414, 2013). "UCP2 has also been shown to be involved in antimicrobial defense by increasing ROS production after infection." (PMID 36499405, 2022). "The levels of MDA and UCP2 were significantly increased due to the infection of S. uberis in WT, TLR2−/−, and TLR4−/− mice (p < 0.05)." (PMID 32098158, 2020). "Upon infection with Toxoplasma gondii, UCP2–/– mice were found to be resistant to infection in comparison to wild type mice." (PMID 32327997, 2020). "Prior studies found that expression of UCP2 was increased in patients with systemic inflammation and infection, while the functional role of UCP2 in LPS-induced lung injury is still unclear." (PMID 27057102, 2016). "It has recently been suggested that Leishmania upregulates UCP2 after infection in order to decrease host ROS levels and thereby suppress macrophage defense machinery." (PMID 23437414, 2013). "Further, infection of BAEC with adenovirus encoding constitutively active UCP-2 (Ad-CA-UCP-2) significantly increased AMPK phosphorylation, indicating that UCP-2 expression was able to activate AMPK in BAEC." (PMID 22532857, 2012). "As expected, adenoviral UCP2 infection significantly reduced insulin release by INS-1E cells (nearly 40% compared to infection with control adenovirus)." (PMID 19065272, 2008). "The infection with Leishmania donovani was reported to disrupt miRNA turnover in macrophages, causing mitochondrial depolarization through induced expression of the OXPHOS uncoupler uncoupling protein 2 (UCP2)." (PMID 34768767, 2021). "During the four days following the infection, with respect to MOI, the UCP2, PDH and AMPK levels have changed significantly at p < 0.001, while MCT1 and PDK1 levels have changed significantly at p < 0.05." (PMID 33093503, 2020). "Uncoupling protein 2 (UCP2) is upregulated in patients with systemic inflammation and infection, but its functional role is unclear." (PMID 27057102, 2016). "UCP2 indeed regulates caspase 1 via the NLRP3 inflammasome by stimulating lipid synthesis, whether during localized or systemic infection." (PMID 36499405, 2022). "Furthermore, with respect to infection duration, the PDK1, AMPK and MCT1 levels have changed significantly at p < 0.001, while UCP2 and PDH levels have changed significantly at p < 0.01." (PMID 33093503, 2020). "Mice lacking UCP2 showed higher survival rates than WT mice following experimental infection with Listeria monocytogenes or Toxoplasma gondii." (PMID 23437414, 2013). "On the other hand, and infection of HUVEC with Ad-DN-AMPK did not alter EPA-induced UCP-2 upregulation." (PMID 22532857, 2012).
cardiovascular diseases (14 papers, 2009 to 2023). "Aside from this, UCP2 has been associated with reductions in mitochondrial oxidative stress, and dysfunction in the protein has been linked to cardiovascular diseases." (PMID 37106780, 2023). "The UCP2 variants were selected based on previous evidence reporting significant associations with IS or with other cardiovascular diseases." (PMID 35629388, 2022). "UCP2 (uncoupling protein 2) plays an important role in cardiovascular diseases and recent studies have suggested that the A55V polymorphism can cause UCP2 dysfunction." (PMID 23537071, 2013). "This review article provided an update on the physiological regulation of UCP2 in the cardiovascular system, and also discussed the involvement of UCP2 deficiency and associated oxidative stress in the pathogenesis of several common cardiovascular diseases." (PMID 30116205, 2018). "A study reported an association of the high-sensitivity C reactive protein (hs-CRP), a biomarker of inflammation that is also a powerful risk marker for cardiovascular disease, with the G(−866)A polymorphism, thus suggesting the role of UCP2 gene in the regulation of the inflammatory response." (PMID 22533685, 2012). "The ability of UCP2 to limit mitoROS production has attracted increasing attention and interest among researchers to investigate its functional role in many cardiovascular diseases in which excessive oxidative stress is present." (PMID 30116205, 2018). "As it was clear that UCP2 played a protective role in cardiovascular disease in our research, upregulating the UCP2 expression could be a potential therapeutic target." (PMID 29547569, 2018). "In this context, UCP2 (uncoupling protein 2), a physiological down-regulator of ROS, might play an important role in cardiovascular diseases." (PMID 23537071, 2013). "In contrast, in models of neurodegenerative and cardiovascular disease, experimental evidence suggests that an increased expression and activity of UCP2 has a beneficial effect on disease progression, implicating a potential therapeutic role for UCP2." (PMID 24281083, 2010). "Other recent reviews have shown that UCP2 and UCP3 reduce ROS production in cardiovascular issue, and dysregulation of UCP2 can lead to cardiovascular disease." (PMID 35628482, 2022). "However, more detailed mechanistic study will be needed to dissect the role of UCP2, the regulation of UCP2 expression, and the cellular responses to the changes of UCP2 expression in normal and stressed situations at different stages of cardiovascular diseases." (PMID 30116205, 2018). "However, the implication of UCP2 degradation in cardiovascular diseases is not fully understood." (PMID 30116205, 2018).
metabolic disorders (13 papers, 2013 to 2025). "Strong evidence suggests that the UCP2 gene polymorphisms may affect the expression/activity levels of UCP2 and subsequently affect related biological processes, which finally result in a variety of diseases, including metabolic diseases and cancer." (PMID 33888769, 2021). "Although previous studies have found a significant interaction between the UCP2 gene and dietary factors on the development of metabolic diseases, the involved pathways and the regulatory mechanism are still unclear and need further research." (PMID 33888769, 2021). "UCP-2 is involved in metabolism disorders and oxidative stress, and it has also been demonstrated that the function of UCPs is to export fatty acids out of the mitochondria when there is an abundance of fatty acids present inside the matrix." (PMID 28587208, 2017). "PPARs are the link between FA (or their derivatives), metabolic diseases, and tissue-specific expression of UCP2 and UCP3." (PMID 27399675, 2016). "However, several studies using the same animal model as in our study pointed out increases in UCP2 expression in obese subjects or in animals with a metabolic disorder in response to a high-fat diet." (PMID 34960036, 2021). "Uncoupling protein 2 (UCP-2), which is involved in metabolic disorders and oxidative stress, was remarkably decreased by xyloketal B treatment compared with the model group." (PMID 28587208, 2017). "Since UCP2 is a critical regulator of cellular glucose and lipid metabolism, we propose that FME may ameliorate metabolic disorders of obese mice partly though the regulation of PPARα signaling pathway." (PMID 24705395, 2014). "PPARs participate in mediating metabolic disorders via downstream genes which are important for adipocyte maturation, lipid accumulation, and insulin-sensitive glucose transport, including PGC1-α, PGC1-β, aP2, LPL, ACC, ACO, CD36, UCP-2 and Glut4." (PMID 24312343, 2013).
neurodegenerative disease (10 papers, 2012 to 2023). A disorder of the central nervous system characterized by gradual and progressive loss of neural tissue and neurologic function. "Due to the potential link between UCP2 gene variants, ROS production and longevity, we investigated in this study, whether UCP2 polymorphisms affect the risk of developing neurodegenerative diseases and whether they account for any variance in brain structure or function." (PMID 28771482, 2017). "This article focuses on UCP2 and its role in neurodegenerative disease, with a focus on neurodegenerative diseases of the eye." (PMID 35628482, 2022). "In this review, we will discuss the role of UCPs in neurodegenerative diseases and injury with a focus on UCP2 because it has the most direct evidence for a role in these conditions, and we know more about its structure and activation." (PMID 35628482, 2022). "Although the exact mechanism(s) of action of UCP2 have yet to be fully defined, the manipulation of the expression or activity of UCP2 leads to such strong effects on neurodegenerative disease that this protein is clearly a high priority as a drug target." (PMID 35628482, 2022). "UCP2 upregulation was also found to be important in terms of providing the benefits of exercise in neurodegenerative diseases via a comparable effect of UCP4 and UCP5 in the reduction of oxidative stress." (PMID 33041765, 2020). "UCP2 and UCP4 are known to protect neurons from mitochondrial dysfunction, oxidative damage, cell survival, preserving ATP synthesis and implicated in neurodegenerative diseases such as in AD and PD." (PMID 28572767, 2017). "UCP2 polymorphisms did not significantly affect occurrence of neurodegenerative diseases in this sample." (PMID 28771482, 2017). "Consequently, irisin/UCP2 might be a potential therapeutic target to improve brain function and prevent or treat neurological and neurodegenerative diseases." (PMID 30983964, 2019). "Especially, it would be interesting to decipher the potential role of microRNAs in downregulating the expression of UCP2 and UCP4, not only in AD, but also in PD and other neurodegenerative diseases." (PMID 28790893, 2017). "Furthermore, targeted overexpression of UCP2 and UCP4 in neurodegenerative diseases could potentially establish their therapeutic as well as neuroprotective effects." (PMID 28790893, 2017). "But for UCP2 and UCP3, there is a consensus that the primary function of UCP2 and UCP3 is to attenuate mitochondrial production of free radical to protect against oxidative damage, degenerative disease and aging rather than to promote gross thermogenesis or energetic inefficiency." (PMID 22313584, 2012).
neurological diseases (6 papers, 2012 to 2026). "Because of the wealth of data showing the role of UCP2 in neurological disease and neuroprotection, this review is focused on this member of the uncoupling protein family." (PMID 35628482, 2022). "The mitochondrial uncoupling protein 2 (UCP2) is known as an endogenous neuroprotective molecule in many neurological disorders." (PMID 30823590, 2019). "The mitochondrial uncoupling protein 2 (UCP2) is expressed in selected regions of the brain and is emerged as an endogenous neuroprotective molecule in many neurological disorders." (PMID 22849356, 2012).
heart disease (4 papers, 2009 to 2022). "Increased expression of FAT/CD36, FATP1, UCP2 and UCP3 have all been implicated in development of lipotoxic heart disease." (PMID 19390571, 2009). "In recent years, UCP2 was found to play an important role in heart disease." (PMID 35284500, 2021).
inflammation (2 papers, 2016 to 2025). Aberrant reaction of the microcirculation characterized by movement of fluid and leukocytes from the blood into extravascular tissues. "In conclusion, UCP2 increased susceptibility to LPS-induced cell death and pulmonary inflammation, most likely via ATP depletion and activation of MAPK signaling following ALI in mice." (PMID 27057102, 2016). "Similarly, MAPK inhibitors SP600125 and SB203580, but not PD98059, significantly reduced TNF-α and IL-1β in BALF of UCP2-Ad + LPS mice compared to UCP2-NC + LPS mice, demonstrating that enhanced UCP2 expression increased LPS-induced lung inflammation via the JNK and p38 MAPK pathways." (PMID 27057102, 2016).
UCP2 also shares sentences with these, for which no sentence is quoted: fibrosis (3 papers); kidney disease (3); myocardial ischemia (3); adenocarcinoma (2); alcoholic liver diseases (2); asthma (2); bladder urothelial cancer (2); cervical squamous cell carcinoma (2); cognitive decline (2); dilated cardiomyopathy (2); multiple sclerosis (2); non-small cell lung adenocarcinoma (2); proliferative diabetic retinopathy (2); pulmonary hypertension (2); abdominal aortic aneurysm (1); acute lung injury (1); acute monocytic leukemia (1); alcoholic hepatitis (1); amyotrophic lateral sclerosis (1); anorexia nervosa (1); aortic regurgitation (1); Apnea (1); B cell lymphoma (1); brain hemorrhage (1); Central hypothyroidism (1); cerebral amyloid angiopathy (1); cervicitis (1); chronic lung disease (1); chronic myeloid leukemia (1); colorectal adenocarcinoma (1).
A further 57 diseases each share a sentence with UCP2 in 1 paper.